MTOR (mechanistic target of rapamycin kinase)
Diseases named in the same sentence as MTOR in open-access papers (continued):
Sharing a sentence is not in itself a finding about the gene and the disease.
tumor (continued). "Synergistic effect of everolimus combined with SSAs seem to result from the action of the these drugs on both tumor cells and their microenvironment through a common molecular target, the PI3K/AKT/mTOR signaling pathway." (PMID 31273555, 2019). "In this neoplasia, both activation of PI3K/mTOR and MEK/ERK pathways promoted the immunosuppressive tumor microenvironment." (PMID 30991686, 2019). "Synergistic anti-tumour responses have been observed by co-targeting the FGFR and PI3K/AKT/mTOR pathway with PI3K, mTOR and Akt inhibitors." (PMID 35582593, 2019). "Subsequently, we examined the expression and the phosphorylation levels of ERK1/2, MEK1/2, PI3K, Akt, mTOR, FAK, RhoA, VEGFR2 and Tie2 in tumor tissue lysates." (PMID 31601793, 2019). "In the cases where non-cancerous adjacent liver tissue was present, we showed an absent/slight positivity of SIRT-3 and a negative expression of p-mTOR, suggesting that the presence of tumor strongly affected SIRT-3 and p-mTOR expression." (PMID 30917505, 2019). "It is also worth noting that all tumour clones in our study displayed sensitivities to the PI3K inhibitor Buparlisib and mTOR inhibitor Vistusertib." (PMID 30736342, 2019). "The cooperation between the IGF-IR and other RTKs activate common downstream targets such as the PI3K/AKT/mTOR and RAF/MEK/ERK pathways, thus promoting tumor proliferation and inhibiting apoptosis." (PMID 31269742, 2019). "However, it is unclear whether CASC9 regulates tumor cell autophagy through the AKT/mTOR pathway." (PMID 30674868, 2019). "In support with this, using two mutant cell lines for IDH and orthotopic mutant IDH tumor model, showed that the treatment with dual PI3K/mTOR inhibitor (XL765), induced a significant reduction in 2HG levels, and enhanced the survival." (PMID 31921637, 2019). "A subset of drugs, including afatinib, dacomitinib, neratinib (EGFR), AZD2014 (mTOR), panobinostat (HDAC), and trametinib (MEK), showed exceptionally high anti-tumor activities across all gynecologic tumors." (PMID 31771620, 2019). "Mechanistically, MLN0128 efficiently inhibited AKT/mTOR signaling and induced strong CCA cell apoptosis, with limited effects on tumor cells proliferation." (PMID 30741922, 2019). "Mechanistically, it was confirmed that tumor-derived TGF-β triggers CD39 and CD73 expression on circulating and tumor-infiltrating MDSCs via activation of mTOR/HIF-1α-signaling." (PMID 31130949, 2019). "PTEN is one of the best well-characterized tumor suppressors, that it governs a variety of cellular processes including survival, proliferation and energy metabolism by suppressing the PI3K/mTOR pathway through its lipid phosphatase activity." (PMID 31200745, 2019). "Although AMP-activated kinase (AMPK) has been characterized as a negative regulator of mTOR activity, our tumor model exhibited activation of both AMPK and mTOR." (PMID 31798532, 2019). "The results of this study demonstrated the increased expression of activated downstream effectors of PI3K/Akt/mTOR and Raf/MEK/ERK pathway in ccRCC tumor tissue compared to adjacent non-tumor tissue." (PMID 31861116, 2019). "Immunoblot analysis of tumour lysates showed that tumours developed from stem‐like HepG2SF1 cells had increased expression of AFP, CD133 and ALDH1A1 as well as upregulation of the Akt/mTOR axis and lower expression of pAMPK, AMPK, pACC and ACC." (PMID 30959553, 2019). "Further work will elucidate how these mTOR-independent activities of the TSC complex contribute to overall cellular metabolic regulation and tumor formation." (PMID 30677091, 2019). "In hypoxic tumor cells, lincRNA-p21 knockdown represses the autophagy via regulating HIF-1/Akt/mTOR/P70S6K signaling pathway." (PMID 30902882, 2019). "PTIM models of PCB490–3, PCB490–4, and PCB490–5 with integrated RNA-seq data indicated common efficacious mechanisms across the heterogeneous tumor sites: epigenetic modifiers (HDAC, EHMT), PI3K/mTOR inhibition, and VEGF (KDR) signaling inhibition." (PMID 31208434, 2019).
tumor (continued). "The increased expression of EMT genes (AKT2, TWIST, and mTOR) in tdTomato− tumors, in CTCs and in mammospheres, highlights the importance of AKT2 in tumor growth and CSC malignancy." (PMID 31357505, 2019). "Combing use of PHN and autophagy blockers exerted enhanced anti-tumor activity, which at least partially through the AMPK/mTOR/p70S6K signal pathway." (PMID 31147451, 2019). "More effective inhibition of tumor growth was achieved by simultaneously targeting both PI3K and mTOR." (PMID 31324855, 2019). "Src/FAK/p-cortactin, Akt/mTOR/c-Myc, UBE2S/hypoxia, and reactive oxygen species (ROS) signaling activated and promoted the metastasis of A431-III tumor cells." (PMID 31731716, 2019). "This study reveals novel insights into the anti-tumor mechanisms of gigantol focused on CSC targeting and destabilizing tumor integrity via suppression of the PI3K/AKT/mTOR and JAK/STAT pathways." (PMID 31861050, 2019). "Specifically, inhibitors of the PI3K/Akt/mTOR pathway or overexpression of autophagy-inducing gene products such as PTEN and Beclin-1 are potentially feasible to treat tumor through autophagy pathway." (PMID 31429768, 2019). "The potential role of the deregulation of PI3K/Akt/mTOR in UPS makes this pathway a potential therapeutic target, but each tumor, given their heterogeneity, has to be evaluated as a unique molecular entity." (PMID 31416195, 2019). "The PI3K/Akt/mammalian target of rapamycin (mTOR) and ERK pathways control the translation of HIF-1α, and HIF-1α activates VEGFs, u-PA, and MMP-2 and -9 to promote tumor metastasis." (PMID 31041568, 2019). "In the present study, the expression of p-mTOR, together with its activators (i.e., p-Akt, p-AMPK) and downstream effectors (i.e., p-p70S6K and p-RPS6) was more intense in the tumour edge." (PMID 30650598, 2019). "Through the inhibition of the oncogenic and pro-survival PI3K/AKT/mTOR axis, PTEN acts as a tumor suppressor by regulating transcription, translation, cell cycle progression, induction of cell death, stimulation of angiogenesis, and stem cell self-renewal." (PMID 31366089, 2019). "Synergistic effects of HDM2 antagonist AMG-232 with many PI3K/Akt/mTOR and Ras/Raf/MEK/MAPK inhibitors were also reported on twenty different human cancer cell lines and in RKO tumor xenograft in vivo experiments." (PMID 31331108, 2019). "ASC tumours showed heterogeneity in MAPK, AKT, and mTOR pathway activities, and were stratified into three mutually exclusive subclasses, namely ‘MAPK/mTOR’, ‘AKT/mTOR’, and ‘Null’." (PMID 31772293, 2019). "Otherwise, in the luminal A subtype cell, upregulated or downregulated special gene sets were involved in tumor-related metabolic pathways, including the TCA cycle, fatty acid metabolism, nitrogen metabolism, peroxisome, mTOR, and AMPK signaling pathways." (PMID 31799941, 2019). "A brief exposure to hypoxia allows tumor cells to survive and progress by activating hypoxia-inducible pathways such as PI3K/AKT/mTOR, NFkB, ERK and chemokines, EMT, migration, and inflammation." (PMID 31077234, 2019). "Accordingly, inhibition of mTOR by rapamycin in cells that overexpress GOLPH3 results in detrimental effects on cell survival, cell proliferation, tumor growth, and cell migration and invasion." (PMID 30779783, 2019). "Marsdenia tenacissima induced apoptosis in tumor cells by regulating the Caspase 3, Caspase 9, Bak, Bax, Bcl-xl, Bcl-2, Fas, and PKC genes, as well as the PI3K/AKT/mTOR and the Hippo signaling pathways." (PMID 31341493, 2019). "mTOR activity is completely inhibited in REDD1-overexpressing cells under normoxic conditions, and continuous hypoxia can weaken its activity in tumor cells." (PMID 31929797, 2019).
tumor (continued). "Thus the inhibition of mTOR might prevent age-related neoplastic disease." (PMID 31174250, 2019). "Many oncogenic and tumor suppressive factors, such as Agrin, Rab7, AKT/mTOR pathway, STAT3, and transcription-3 signalling have been identified for HCC." (PMID 31164410, 2019). "We further investigated HIF-2α, PI3K, mTOR and Akt expression and distribution in STAM mouse tumour frozen sections." (PMID 31796646, 2019). "Another PI3K/mTOR dual inhibitor, LY3023414, also showed potent cytotoxic activity in several cSCC cell lines as well as the in vivo tumor xenograft models." (PMID 31370278, 2019). "In summary, Ori displayed anti-tumor bioactivity and decreased cisplatin resistance by apoptotic signaling activation, which was modulated by AMPK/Akt/mTOR-dependent autophagy inhibition." (PMID 31475112, 2019). "Quantification of p-PRAS40/p-S6 levels (indicators for AKT and mTOR, respectively), and of p-ERK (indicator for MAPK pathway), confirmed that after 24 h of culturing tumor tissue remain viable and active." (PMID 30723707, 2019). "The number of tumor cells positive for Ki-67, a cell proliferation marker, and p-S6RPs240/244, a protein indicating activity of the PI3K/mTOR pathway, was substantially lower in IB136 and resIB136 xenografts treated with BEZ235 compared with control tumors." (PMID 30683135, 2019). "In fact, the levels of phosphorylated (p‐) forms of AKT, mTOR, and MAPK were 3‐ to 10‐fold higher in the PH026 tumor." (PMID 30499260, 2019). "Next, to directly determine the CD8+ T‐cell–intrinsic requirement for PI3K/Akt/mTOR signalling in PD‐L1‐mediated rescue, we examined p‐PI3K, p‐Akt and p‐6s expression in the CD8+ T cells and tumour cells of the four groups by Western blotting." (PMID 30714229, 2019). "In this study, we investigated the effect of eribulin and a mTOR inhibitor, either alone or in combination, on the PI3K/AKT/mTOR pathway and tumor growth in TNBC." (PMID 31480338, 2019). "Conversely, in HCC with PTEN null expression, it would determine an even stronger AKT/mTOR pathway activation through AKT3 upregulation, contributing to tumor cell proliferation and invasion." (PMID 31805631, 2019). "PD-L1 expression can be induced by inflammatory cytokines or tumor-cell intrinsic signaling, including NF-κB, MAPK, PI3K, mTOR and JAK/STAT." (PMID 30925913, 2019). "In low oxygenated cells, HIF-1α, mTOR, TGFβ and Stat3 levels were shown to increase CD133 expression in tumour cells, promoting GSC formation and proliferation." (PMID 31690341, 2019). "The competitive binding of lncRNA-PAGBC and tumour suppressive miR-133b and miR-511 are required for its ability on promoting tumour growth and metastasis and activating the AKT/mTOR pathway." (PMID 30971290, 2019). "There were significant decreases in p‐AKT/AKT, p‐mTOR/mTOR, and PD‐L1 in DTLL‐treated tumor samples with the same inhibitory trends in the ratios of p‐EGFR/EGFR and p‐HER2/HER2." (PMID 30681288, 2019). "In xenografted mouse model, we measured the tumor size before and after the Adv-mfn2 or Adv-control treatment, and analyzed the expression of Cyclin D1, Ras, Myc, ERK1/2, NF-κB p65, mTOR proteins by western blot." (PMID 31384172, 2019). "LKB1/AMPK signaling downregulates SNAIL and ZEB1, which are the EMT marker proteins, and inhibits the invasion and migration of tumor cells, by regulating signaling pathways, such as those involving NF-κB, AKT, FOXO3, TGF-β, and mTOR." (PMID 31027222, 2019). "We finally investigated the specific molecular mechanism of the anti-tumor effect of PHN combined with autophagy inhibitors and focused on AMPK/mTOR/p70S6K signaling pathway." (PMID 31147451, 2019). "The combination of the mTOR inhibitor AZD8055 with the BH3-mimetic, ABT-263, induced a decreased phosphorylation of 4EBP1 and S6, also lowering MCL-1 expression and inducing tumour regression in vivo." (PMID 30795552, 2019).
tumor (continued). "Inhibition of either mTOR or AKT activities rescued the observed hyperproliferation in autophagy-inhibited SW480 and reduced tumor growth." (PMID 31383875, 2019). "The inhibition of tumor cell migration observed in wound-healing and transwell assay was found to be due to MMP-9 suppression that is controlled by AKT/mTOR axis." (PMID 31052558, 2019). "Through a number of downstream effectors, such as mTOR, p-4E-BP1 and p-S6K, Akt plays a key role in tumor cell survival and proliferation." (PMID 30943918, 2019). "Being one of the most frequently activated signaling pathways in tumor cells, numerous efforts have been made to develop PI3K/AKT/mTOR targeted therapies." (PMID 30741922, 2019). "In this study, based on our in vitro and in vivo results and literature data, we introduce a novel, comprehensive network of common tumor-related proteins, such as PD-1, MET, RAF1, STAT3, BCL2, or mTOR." (PMID 31681332, 2019). "PD-L1 can be directly regulated by intracellular signaling pathways, mainly deregulated in many tumor types (RAS/RAF/MEK, PI3K/AKT/mTOR, JAK, and STAT) or by the IFN-Υ signaling, as a consequence of IFN-Υ release by immune cells in the tumor microenvironment." (PMID 31500143, 2019). "For the patient-derived (xenograft) tumour cells, cisplatin yielded a modest effect (46% reduction) and the targeted-therapy (EGFR and mTOR inhibitors) revealed a strong effect (80–90% reduction)." (PMID 31331338, 2019). "It is well documented that miR-21 targets tumor suppressors such as PDCD4 and phosphatase and tensin homolog (PTEN), both of which suppress expressions of PI3K, STAT3, mTOR, and β-catenin." (PMID 31878245, 2019). "In clinical PACs, the co-activation of MAPK and p38MAPK was observed in only one out of ten pp38positive tumours (PAC_4, ‘MAPK/mTOR’ signature)." (PMID 31772293, 2019). "Anti-tumor activity of MP1 in cell culture and in tumor bearing mice was potentiated by TEM, by mechanisms that likely involve the mTOR pathway." (PMID 31455317, 2019). "New-generation mTOR inhibitors against ATP-binding pocket inhibit both TORC1 and TORC2 and demonstrate more potent anti-tumor effects in vitro and in vivo." (PMID 30682771, 2019). "Some well-characterized tumor suppressors, such as PTEN and TSC1/2, negatively regulate the protein kinase mTOR and induce autophagy." (PMID 30987661, 2019). "mTOR is a downstream effector of the PI3K/Akt axis, and MMPs are regulated by CXCR4 in tumor metastasis through the PI3K/Akt signaling pathway." (PMID 32047724, 2019). "Recently, sirolimus, a drug that targets the mammalian target of rapamycin (mTOR) downstream of the VEGF pathway, was effective in regressing tumor mass in a patient with segmental IH who had been unresponsive to treatment." (PMID 29652858, 2018). "A total of seven factors were identified, including age, tumor diameter, surgery, and CK7, Ki-67, PTEN, and mTOR expression, and these factors were integrated into a model for the prediction of high grade risk." (PMID 30619768, 2018). "Moreover, the role of the mTOR pathway in macrophage activity is involved not only in M1/M2 polarization, but also in processes, such as autophagy, which could indirectly influence the outcome of tumor progression." (PMID 30126252, 2018). "IHC staining of sections of tumor xenografts showed that upregulation of BART1-5P significantly reduced the expression of AMPKα1 but increased HIF-1α, GLUT1, LDHA and mTOR when compared with the relative control." (PMID 30557400, 2018). "What’s more, by knocking down the GOLPH3 expression in HCC cells, the expression of p-mTOR (Ser2448), p-Akt (Ser473) and p-S6 K1 (Thr389) were remarkably decreased in the HCC cell lines and in the xenograft tumor model." (PMID 29914442, 2018). "The xenograft mouse model further confirmed that metformin inhibited tumor growth by upregulation of AMPK and downregulation of mTOR." (PMID 29554968, 2018).
tumor (continued). "In an integrated metabolomics approach in HepG2 liver cancer cells, high dose of MTF mediated, under high glucose concentration, hypoglycemic effects, reduced tumor cell proliferation, and mediated apoptosis by activating AMPK/mTOR pathway signaling." (PMID 30241339, 2018). "The GABAB receptor antagonist exhibited anti-tumor effects at the G1/S cell cycle checkpoint and induced apoptosis via dual inhibition of the PI3/Akt/mTOR and MAPK signaling pathways." (PMID 29514603, 2018). "Targeted NGS of MTOR, TSC1 and TSC2 genes was performed on DNA extracted from formalin-fixed paraffin-embedded primary tumor and hepatic metastasis, and the patient’s peripheral blood (TruSeq Custom Amplicon Low Input; Illumina)." (PMID 29764404, 2018). "So we examine the expression of pElk-1, Elk-1, mTOR, HIF-1α, VEGF-A in HUVECs, which were treated by tumor supernatant and inhibitors." (PMID 30250188, 2018). "VEGFR2 downstream signalling pathways include both PI3K/AKT/mTOR and MAPK signalling cascades, which play an important role in proliferation, angiogenesis and metastasis of tumour cells." (PMID 30589500, 2018). "PFE administration also ameliorates tumor growth/progression/angiogenesis of B(a)P or NTCU induced primary lung tumors in A/J mice by dwindled activation of NF-κB, MAP kinase pathways, and mammalian target of rapamycin (mTOR) signaling." (PMID 29702555, 2018). "Targeted next generation sequencing (NGS) of MTOR, TSC1 and TSC2 genes in the primary tumor, metastasis and blood of the patient, revealed one inactivating TSC2 mutation (c.2739dup; p.K914*) in the tumor cells." (PMID 29764404, 2018). "We demonstrate co-activation of the PI3K/mTOR and MAPK pathways in murine and human tumors and show that in vivo concurrent inhibition of mTOR and MEK results in sustained tumor regression." (PMID 29872503, 2018). "In tumour cells bearing activated Akt, TSC2 is inhibited by phosphorylation, leading to an increase in Rheb-GTP and mTOR activation." (PMID 29515798, 2018). "Given the striking effects of the TME in promoting tumour progression and chemotherapeutic resistance, we reasoned the efficiency of in vivo targeting of TAK1 by comparing with that of inhibiting mTOR or p38 in chemotherapeutic settings." (PMID 29712904, 2018). "In the HCC tissue specimens, immunochemistry revealed that the protein expression of p-mTOR (Ser2448), p-Akt (Ser473), and p-S6 K1 (Thr389) in the HCC tumor tissues were significantly higher than those in the paired normal groups." (PMID 29914442, 2018). "Accordingly, dual PI3K/mTOR inhibitors that block both PI3K/Akt and mTOR have been proposed to achieve better anti-tumor outcomes." (PMID 30555320, 2018). "Treatment of radioresistant adult glioblastoma cells with the dual mTOR and P13K inhibitor NVP-BEZ235 was found to lead to cell growth arrest and a reduction in tumor proliferation after radiotherapy." (PMID 30443293, 2018). "The expression of phosphorylated mTOR, AKT and S6 K1 were significantly higher in HCC tumor tissue and cell lines compared with those in normal liver tissues (p < 0.05)." (PMID 29914442, 2018). "Immunohistochemical staining indicated a close relationship between the inhibition of tumor growth and the PI3K/AKT/mTOR signal pathway." (PMID 29614812, 2018). "Studies on cell lines from small bowel NETs derived from primary tumours, liver metastases and metastatic lymph nodes, highlighted the strong PI3K/Akt/mTOR pathway activation in respect to normal enterochromaffin-like cells." (PMID 29509701, 2018). "For example, Bogani and her group investigated the effects of mTOR inhibitors in combination with JAK2 inhibitors, in in vitro MyeloProliferative Neoplasms (MPN) cells." (PMID 29351204, 2018). "Our in vivo and in vitro findings showed that blocking mTOR and activating AMPK prevented tumor progression in a tumor xenograft mouse model." (PMID 30107094, 2018).